FGFR1 (fibroblast growth factor receptor 1)
Diseases named in the same sentence as FGFR1 in open-access papers (continued):
Sharing a sentence is not in itself a finding about the gene and the disease.
rhabdoid tumor (4 papers, 2013 to 2021). An aggressive malignant embryonal neoplasm usually occurring during childhood. "We show that PDGFRα levels are regulated by SMARCB1 expression, and assessment of clinical specimens documents the expression of both PDGFRα and FGFR1 in rhabdoid tumor patients." (PMID 27783942, 2016). "To verify the clinical relevance of our findings, we evaluated the mRNA levels of PDGFRA and FGFR1 in an RNA sequencing (RNA-seq) dataset of 23 primary rhabdoid tumor (RT) patient specimens composed of 12 MRTs and 11 AT/RTs." (PMID 27783942, 2016). "It differentially regulated EGFR, FGFR1 and FGFR2, leading to downregulation of EGFR in epithelioid sarcoma and to mesenchymal-to-epithelial transition whereas in rhabdoid tumor cells, EGFR was strongly upregulated and reinforced the mesenchymal phenotype." (PMID 34281526, 2021). "Furthermore, we did not observe increased expression levels of FGFR1 or FGFR2 in the atypical teratoid/rhabdoid tumor (AT/RT) cell line BT16 (data not shown), indicating that the correlation of SNF5-deficiency and elevated expression of FGFRs might be true only for non-CNS rhabdoid tumors." (PMID 24204904, 2013).
rickets (4 papers, 2014 to 2020). Bone softening and weakening usually caused by deficiency or impaired metabolism of vitamin D. Deficiency of calcium, magnesium, or phosphorus may also cause rickets. "In addition to the improvement in serum biochemistries in Hyp mice by conditional deletion of Fgfr1 in osteocytes, there was a partial rescue of the hypophosphatemic rickets phenotype in the compound Hyp;Fgfr1Dmp1-cKO-null mice." (PMID 25089825, 2014).
Saethre-Chotzen syndrome (4 papers, 2009 to 2023). Saethre-Chotzen syndrome (SCS) is an inherited craniosynostosis syndrome characterized by unilateral or bilateral coronal synostosis, facial asymmetry, ptosis, strabismus and small ears with prominent crus, among other less common manifestations. "The majority of patients with Saethre-Chotzen syndrome (SCS) present loss-of-function mutations in transcription factor TWIST1 which is thought to negatively regulate FGFR1, 2 and 3 and the osteogenic transcription factor Runx2." (PMID 20108486, 2009). "Genes associated with the other syndromes (e.g., Carpenter [RAB23 gene, MEGF8 gene], Apert [FGFR2 gene], Crouzon [FGFR2 gene], Pfeiffer [FGFR2 gene, FGFR1 gene], and Saethre-Chotzen syndromes [TWIST1 gene]) were analyzed by WES analysis and none of these mutations were found on the patients." (PMID 34348791, 2021).
Sepsis (4 papers, 2018 to 2023). Sepsis is defined as life-threatening organ dysfunction caused by a dysregulated host response to infection. "Recent reports showed that sepsis causing vascular injury may not only induce endothelial glycocalyx destruction but also impair fibroblast growth factor receptor 1/exostosin-1-mediated glycocalyx reconstitution." (PMID 29520236, 2018). "A report showed that although the HS fragments are able to activate FGF2-FGFR1 signaling, HS biosynthesis by EXT1 and FGFR1 expression are downregulated in sepsis." (PMID 36865384, 2023). "Yang and colleagues investigated the endogenous mechanisms underlying homeostatic pulmonary glycocalyx reconstitution, and identifies FGFR1 as a critical mediator of glycocalyx repair and is suppressed during sepsis." (PMID 36183124, 2022). "Indeed, FGFR1 is suppressed in sepsis, and an increase in FGFR1 expression attenuates pulmonary inflammation in ventilator induced lung injury." (PMID 36969192, 2023).
spina bifida (4 papers, 2016 to 2023). A congenital neural tube defect in which vertebrae are not fully formed. "A hypomorphic Fgfr1 allele has also been reported to cause spina bifida and skeletal malformations similar to those reported here." (PMID 37756583, 2023). "Embryos in which exon 3 of Fgfr1 is globally deleted, preventing expression of the Fgfr1α isoform, also develop fully penetrant spina bifida, confounded by severe dysmorphology and early lethality." (PMID 37756583, 2023). "Mutation or reduced expression of numerous members of Wnt, FGF, or BMP pathways, for example FGFr1 and Axin, can lead to exencephaly and spina bifida." (PMID 32582689, 2020). "The ability of embryos with caudally deleted Fgfr1 to achieve delayed yet complete PNP closure is surprising, not only because of the level of dysmorphology their closure process overcomes, but also because alternative disruptions of the same gene cause open spina bifida in mice." (PMID 37756583, 2023). "Apart from the 3 mutants with only spina bifida (Fgfr1, Shp2, and Gcm1) which have 2 neural tubes with one notochord, 2 other mutants with spinal defect but no spina bifida share the same predicament." (PMID 28286691, 2017).
steatosis (4 papers, 2012 to 2025). Increased lipid within the cytoplasm of cells. "A lack of increases in MTP and MCAD in the liver under prolonged starvation is also consistent with the increase of hepatic lipogenesis and steatosis in the adipose FGFR1 deficient mice." (PMID 23106963, 2012). "Adipocyte-specific deletion of FGFR isotypes, FGFR1 and FGFR2 show that specifically adipose FGFR1 mediates indirect effects in liver that are most significant under starvation conditions which causes hepatic stress and steatosis." (PMID 23106963, 2012). "Studies with WAT-specific FGFR1 KO mice indicate that FGF21 signaling through FGFR1/β-klotho in WAT protects the liver against steatosis during prolonged fasting by curbing lipolysis in WAT." (PMID 26834701, 2015). "We propose an axis of hepatocyte-adipocyte cooperation mediated by hepatocyte FGF21 and adipocyte FGFR1 that serves to protect and mete out lipid reserves systemically while protecting the liver against excessive steatosis and damage under metabolic extremes and general hepatic stress." (PMID 23106963, 2012). "The moderate but consistent upregulation of Fgfr1 and Ppargc1a observed in mice with less hepatic involvement supports the hypothesis that these genes may participate in adaptive metabolic pathways that mitigate steatosis." (PMID 41465464, 2025). "The forced increase in NEFA level from adipocytes due to FGFR1 deficit under prolonged starvation, likely in part resulted in the observed compensatory increases of hepatic and serum FGF21 through hepatic PPARα, and the elevated hepatic lipogenesis and steatosis as well." (PMID 23106963, 2012).
adenosquamous carcinoma (3 papers, 2015 to 2023). A carcinoma composed of malignant glandular cells and malignant squamous cells. "This hypothesis was confirmed by an additional FGFR1-amplified adenosquamous carcinoma from another patient with an unknown response to FGFR inhibition." (PMID 37606995, 2023).
ameloblastoma (3 papers, 2013 to 2026). The most common odontogenic tumor, arising from the epithelial component of the embryonic tooth and usually affecting the molar-ramus region of the mandible or maxilla. "FGFR1 was expressed in the tumor and stromal cells of ameloblastoma, the expression of FGFR2 was investigated only in the tumor cells." (PMID 24002438, 2013). "The finding of an FGFR1 mutation in AFO may suggest a biological relationship between odontogenic tumors with ameloblastic features, such as ameloblastoma, ameloblastic fibroma, and AFO." (PMID 39907837, 2025). "In the follicular ameloblastoma, FGFR1 was strongly expressed in the stromal cells." (PMID 24002438, 2013). "Next, we performed immunohistochemistry to analyze the expression of FGFR1 and FGFR2, the specific receptors of FGF7 and FGF10, in the ameloblastoma specimens and in AM-1 cells." (PMID 24002438, 2013). "The expression of FGF7, FGF10, FGFR1 and FGFR2 was detected in ameloblastoma cells and AM-1 cells, while that of FGF3 was not." (PMID 24002438, 2013).
angiosarcoma (3 papers, 2022 to 2025). A malignant tumor arising from the endothelial cells of the blood vessels. "Next generation sequencing of the angiosarcoma revealed an exon 14 mutation in FGFR1 (NM023110.2 (FGFR1):c.1966A>G) as the only pathogenic mutation." (PMID 35204340, 2022). "FGFR1 has been associated with suppression of metastasis in angiosarcoma, so loss-of-function mutations could be associated with metastasis." (PMID 41301029, 2025). "As FGFR1 is highly expressed in human angiosarcoma cells, FGF1-PIGN treatment may inhibit the growth, invasion and migration of human angiosarcoma cells as well as ISOS-1 cells." (PMID 38637316, 2024).
bone tumor (3 papers, 2015 to 2023). "Mutations of the fibroblast growth factor receptor type 1 (FGFR1) genes are one of the characteristic molecular changes of giant-cell-rich bone tumors." (PMID 37384251, 2023). "In this study, it was found that about 34% of Chinese bone tumor patients harbored actionable targeted mutations, including CDKN2A, PTEN, FGFR1/2/3, NF1, and NTRK1/2/3." (PMID 35756627, 2022). "FGFR1 mRNA and/or protein levels are both significantly elevated in distinct cancers (e.g., breast and bone cancer), suggesting that the FGFR1 receptor is a rational target for therapeutic intervention." (PMID 26201468, 2015).
brainstem glioma (3 papers, 2017 to 2022). "A study analyzing the molecular profile of adult brainstem gliomas reported a surprisingly high FGFR1 mutation frequency in 18% of patients (13/73 cases)." (PMID 35018490, 2022).
CHARGE syndrome (3 papers, 2011 to 2022). CHARGE syndrome is a multiple congenital anomaly syndrome characterized by the variable combination of multiple anomalies, mainly Coloboma; Choanal atresia/stenosis; Cranial nerve dysfunction; Characteristic ear anomalies (known as the major 4 C's). "These include the genes KAL1, FGFR1, FGF8 which encodes the ligand of FGFR1, PROKR2 and PROK2, NELF (nasal embryonic factor) and mutations in CHD7 associated with the CHARGE syndrome." (PMID 24204987, 2013). "Although CHD7 was originally considered to be the causative gene for CHARGE syndrome, subsequent research showed that CHD7 mutations can also be detected in KS patients lacking mutations in KAL1, FGFR1, PROK2, and PROKR2." (PMID 34231173, 2022).
chondrosarcoma (3 papers, 2018 to 2024). A malignant cartilaginous matrix-producing mesenchymal neoplasm arising from the bone and soft tissue. "To investigate whether FGF4, FGF8, and FGF9 induce differential signaling via FGFR1c (referred to as FGFR1 here), we used rat chondrosarcoma (RCS) chondrocytes, an immortal chondrocyte cell line used to model proliferating chondrocytes in the developing limb." (PMID 38568193, 2024). "In chondrosarcoma animal models, treatment with VEGFR2/PFGF-β/FGFR1 inhibitor SU668 resulted in tumor growth inhibition." (PMID 29546033, 2018).
cognitive deficits (3 papers, 2021 to 2025). "Ganoderma lucidum polysaccharides promoted neural progenitor cell proliferation to enhance neurogenesis and alleviated cognitive deficits in transgenic AD mice, promoted self-renewal of neural progenitor cell, enhanced the activation of FGFR1 and its downstream ERK and AKT cascades in vitro." (PMID 38075226, 2023). "GLPs enhance the activation of fibroblast growth factor receptor 1, and its downstream extracellular signal-regulated kinase and AKT cascades, promote the proliferation of neuropodocytes in AD mice, and reduce cognitive deficits." (PMID 34074054, 2021).
congenital hypogonadotropic hypogonadism (3 papers, 2019 to 2022). Congenital hypogonadotropic hypogonadism (CHH) is a rare disorder of sexual maturation characterized by gonadotropin (Gn) deficiency with low sex steroid levels associated with low levels of follicle stimulating hormone (FSH) and luteinizing hormone (LH). "Only rarely have mutations in genes known to cause aberrations of the hypothalamic-pituitary-gonadal axis been identified in cases of delayed puberty, and the majority of these are in relatives of patients with congenital hypogonadotropic hypogonadism (CHH), for example in the FGFR1 and GNRHR genes." (PMID 31293522, 2019).
ductal breast adenocarcinoma (3 papers, 2018 to 2021). "Furthermore, through siRNA and a small-molecule inhibitor of FGFR1 (SU5402), they proved that inhibition of FGFR1 was capable of blocking survival of the ductal carcinoma cell line MDA-MB-134." (PMID 30011957, 2018).
endometriosis (3 papers, 2013 to 2023). The growth of functional endometrial tissue in anatomic sites outside the uterine body. "The IHC staining indicated the protein level of p-FGFR1 in DRG tissues from endometriosis rats were increased, whereas the p-FGFR1 level downregulated after NSC12 administration (*P < 0.05)." (PMID 36845134, 2023). "The results of the present work showed that increased concentration of FGF2 around nerve fibers in endometriosis interact with elevated FGFR1 level on nerve fibers and trigger endometriosis-related pain symptoms." (PMID 36845134, 2023). "Inhibition of FGFR1 by shFGFR1 in an endometriosis model of nude mice could prevent lesion formation and dysmenorrhea severity, also providing a new direction in targeting FGFR1 in endometriosis." (PMID 36845134, 2023). "High expressions of FB receptors associated with pro-fibrosis and adhesion, such as FGFR1, FGFR4, ICAM, and CD44, were activated by ligands in immune cells, suggesting that alternate endometriosis immune cells played an important role in promoting lesion development." (PMID 34233737, 2021). "Administration of FGFR1 inhibitor remarkably elevated the mechanical pain threshold (MPT) and prolonged the heat source latency (HSL) in a rat model of endometriosis." (PMID 36845134, 2023). "The concentration of FGF2 in ascites and the protein level of fibroblast growth factor receptor 1 (FGFR1) were higher in patients with endometriosis than in those without endometriosis, and they were correlated with pain symptoms." (PMID 36845134, 2023). "Ovarian endometriotic tissues from endometriosis patients with endometriosis-related pain symptoms had a higher FGFR1 level than those from patients without endometriosis-related pain." (PMID 36845134, 2023). "In addition, introducing the fibroblast growth factor receptor 1 (FGFR1) inhibitor NSC12 could reverse the effect of FGF2 in DRG cells and reduce the pain hyperalgesia of endometriosis rats." (PMID 36845134, 2023).
epilepsy (3 papers, 2019 to 2023). A brain disorder characterized by episodes of abnormally increased neuronal discharge resulting in transient episodes of sensory or motor neurological dysfunction, or psychic dysfunction. "Some groups thus separate epilepsy-associated tumors into those with FGFR1 mutations (DNTs) and those with BRAF mutations." (PMID 37525202, 2023). "A boy (case 26) with HH who carried an FGFR1 variant had novel extragenital features, including pulmonary hypoplasia, bronchiectasis, primary hypothyroidism, hypoparathyroidism and epilepsy." (PMID 35432193, 2022).
esophageal adenocarcinoma (3 papers, 2017 to 2025). A malignant tumor with glandular differentiation arising predominantly from Barrett mucosa in the lower third of the esophagus. "In ESCC, FGFR1 amplification is more prevalent than esophageal adenocarcinoma, and an overexpression of the FGFR1 gene is shown to independently predict prognosis in ESCC patients." (PMID 40722739, 2025).
essential thrombocythemia (3 papers, 2021 to 2022). A chronic myeloproliferative neoplasm that involves primarily the megakaryocytic lineage. "No rearrangement of PDGFRA, PDGFRB, FGFR1, or PCM1-JAK2; the Philadelphia chromosome; or BCR-ABL1 gene fusion should be detected as any diagnostic criteria for polycythemia vera (PV), essential thrombocythemia (ET), and primary myelofibrosis (PMF)." (PMID 34684141, 2021).
extraventricular neurocytoma (3 papers, 2020 to 2024). "In contrast, FGFR1-TACC1 fusion is a distinctive alteration of extraventricular neurocytoma in addition to a small number of other rare FGFR1 and FGFR3 fusions." (PMID 35018490, 2022).
hypereosinophilic syndrome (3 papers, 2014 to 2023). Hypereosinophilic syndrome (HES) constitutes a rare and heterogeneous group of disorders, defined as persistent and marked blood eosinophilia and/or tissue eosinophilia associated with a wide range of clinical manifestations reflecting eosinophil-induced tissue/organ damage. "Hypereosinophilic syndrome (HES) is a rare clinical disease that affects 0.036/100,000 patients, with a minority of patients having associated genetic markers which can encompass PDGFRA/B or FGFR1 mutations." (PMID 32617216, 2020).
Intellectual disability (3 papers, 2015 to 2024). "Additionally, a literature review allowed us to conclude that KAL1 protein at high levels may interfere with FGFR1 signaling activity, most probably indirectly giving rise to ectrodactyly, intellectual disability, and genital anomalies." (PMID 25339597, 2015).
kidney cancer (3 papers, 2021 to 2023). Primary or metastatic malignant neoplasm involving the kidney. "We previously demonstrated FGFR1 endocytosis defects in human von Hippel-Lindau (hVHL) mutant kidney cancer cells, resulting in excessive accumulation of FGFR1 on the PM and increased signaling activity." (PMID 38136383, 2023).
liposarcoma (3 papers, 2020 to 2025). A usually painless malignant tumor that arises from adipose tissue. "In liposarcoma, activating mutations were found in FGFR1 and FGFR3, as well as overexpression of FGFR1 and FGFR4, both of which are related to poor prognosis in patients." (PMID 41300532, 2025). "Receptor tyrosine kinase (RTK) genes DDR2 (discoidin domain receptor tyrosine kinase 2), ERBB3 (Erb-B2 receptor tyrosine kinase 3), FGFR1 (fibroblast growth factor receptor 1), and ROS1 (ROS Proto-Oncogene 1) are also amplified in dedifferentiated liposarcoma." (PMID 33498189, 2021).
nasopharyngeal carcinoma (3 papers, 2021 to 2024). A carcinoma arising from the nasopharyngeal epithelium. "In nasopharyngeal cancer, Circlpo7 interacts with cytoplasmic YB1, promoting the phosphorylation of YB1 at S102, further promoting YB1’s nuclear translocation, and activating FGFR1, TNC, and NTRK1 transcription, thereby promoting nasopharyngeal cancer metastasis and resistance to cisplatin." (PMID 39497723, 2024). "In another study, the association of Epstein–Barr virus (EBV) with nonkeratinizing nasopharyngeal cancer (NPC) was explained through the perspective of FGFR1 signaling in the LMP1 pathway." (PMID 34063231, 2021).
oral squamous cell carcinoma (3 papers, 2014 to 2021). "Considering these previous findings, IFI44L might be a promising agent serving as a tumor suppressor in oral squamous cell carcinoma, possibly through acting on the FRS-mediated FGFR1, FGFR3, and downstream signaling pathways." (PMID 34903206, 2021).
pilomyxoid astrocytoma (3 papers, 2017 to 2022). An astrocytic tumor of uncertain relation to pilocytic astrocytoma. "FGFR1 rearrangement: An FGFR1 rearrangement was detected in one of 19 (5%) patients with pilocytic or pilomyxoid astrocytomas who had this testing performed on all paired surgical specimens." (PMID 33153497, 2020).
pituitary hormone deficiency (3 papers, 2025). "On the other hand, the possibility of combined pituitary hormone deficiency (CPHD) should be considered since heterozygous FGFR1 variants are reported in 2.7% of cases of CPHD." (PMID 40141355, 2025). "We first describe our study’s index kindred, in which a proband and his daughter with the same rare variant in the Fibroblast Growth Factor Receptor 1 (FGFR1) gene developed an early-onset pituitary tumour and combined pituitary hormone deficiency (CPHD), respectively." (PMID 40064730, 2025). "A systematic review of the literature regarding the prevalence of FGFR1 gene defects in patients with hypopituitarism was conducted as well, to shed light on the different phenotypes associated with this genetic abnormality." (PMID 40434549, 2025).